KTN1 (kinectin 1)
Diseases named in the same sentence as KTN1 in open-access papers:
KTN1 is named in the same sentence as 26 diseases in open-access papers, as found by Europe PMC text mining. Sharing a sentence is not in itself a finding about the gene and the disease. The quoted sentences say what the papers report.
cutaneous squamous cell carcinoma (5 papers, 2019 to 2024). "For instance, KTN1 was significantly upregulated in cutaneous squamous cell carcinoma (CSCC), and a MALAT1-KTN1-EGFR axis, which also existed in melanoma and cervical cancer cells, was demonstrated to promote the development of CSCC cells." (PMID 34234850, 2021). "Moreover, in skin, the lncRNA MALAT1 was shown to interact with the transcription factor MYC and bind to the promoter region of the Kinectin 1 (KTN1) gene, thus contributing to enhancement of epidermal growth factor (EGF) signaling in cutaneous squamous cell carcinoma." (PMID 38542324, 2024).
breast carcinoma (4 papers, 2021 to 2023). "Our previous study also probed that some TFs, including Yin Yang 1 (YY1), as a molecular target for basal-like breast cancer, could promote epithelial-to-mesenchymal transition progression of the basal-like subtype through trans-activating the Kinectin 1 gene." (PMID 36814821, 2023). "Therefore, this functional study was performed to decipher the regulatory cohort of KTN1 in high‐grade breast cancer." (PMID 35811688, 2022). "KTN1 expression in TNBC was increased compared with adjacent tissues or luminal or Her2 subtypes of breast cancer, and TNBC patients with high KTN1 expression have poor prognosis." (PMID 34219129, 2021). "In addition, we also found that subunit p65 of NF-kappa(κ)B (NF-κB/p65), as a TF, could be phosphorylated by Kinectin 1, and these complex could activate the expression of chemokine CXCL8 in invasive basal-like breast cancer." (PMID 36814821, 2023). "To identify the pro-carcinogenic role of KTN1 in vivo, we assessed the effects of KTN1 overexpression, and CXCL8 knockdown by siRNA oligos of cholesterol and dimethoxy-modified in KTN1 overexpressed cells on MDA-MB-231 xenograft mammary tumor growth in NOD/SCID/IL2rγ null (NSG) mice." (PMID 34219129, 2021). "Recently, we reported that kinectin 1 (KTN1), a member of the kinesin‐binding protein family, promotes cell invasion of triple‐negative breast cancer and high‐grade breast cancer cells by augmenting the NF‐κB signaling pathway." (PMID 35811688, 2022).
hepatocellular carcinoma (2 papers, 2021 to 2024). A malignant tumor that arises from hepatocytes. "KTN1, as an LncRNA, promotes tumor growth in hepatocellular carcinoma and exacerbates tumor progression in ovarian cancer." (PMID 40625890, 2024).
schizophrenia (2 papers, 2021 to 2023). A major psychotic disorder characterized by abnormalities in the perception or expression of reality. "These schizophrenia-risk variants had potential or significant regulatory effects on the KTN1 mRNA expression in cortical or subcortical structures, the GMVs of subcortical structures, the SA and/or TH of about 50% cortices." (PMID 36890161, 2023). "Our findings that schizophrenia-risk alleles regulated KTN1 mRNA expression, and SA and TH of cortices in limbic system (amygdala, hippocampus, hypothalamus, and cingulate gyrus) and insula supported this implication." (PMID 36890161, 2023). "The schizophrenia-risk alleles increased the KTN1 mRNA expression in prefrontal cortex (BA9) and the TH of frontal pole, superior frontal, rostral middle frontal, and lateral orbito-frontal cortices, and pars opercularis." (PMID 36890161, 2023). "Regionally, these schizophrenia-risk KTN1 alleles regulated the mRNA expression, GMVs, SA and/or TH widely across numerous brain regions, including both cortices and subcortical structures." (PMID 36890161, 2023). "In this study, we examined a dense set of SNPs across entire KTN1, in order to identify variants that were associated with schizophrenia consistently across independent samples, which reduced false positives and improved the reliability of findings." (PMID 36890161, 2023). "We found that across entire KTN1, only 26 SNPs within the same block (r2 > 0.85) were associated with schizophrenia across ≥ 2 independent samples (7.5 × 10–5 ≤ p ≤ 0.048)." (PMID 36890161, 2023). "After FDR correction, associations between SNPs and risk for schizophrenia in Europeans, KTN1 mRNA expression in brain in GTEx, and ICV and BG GMVs remained significant." (PMID 36890161, 2023). "And then, we explored the regulatory effects of these schizophrenia-risk variants on KTN1 mRNA expression, GMVs of subcortical structures, and surface area (SA) and thickness (TH) of different cortical regions throughout whole brain." (PMID 36890161, 2023). "We identified 26 risk KTN1 variants that were located within the same block, spanned entire KTN1, and were significantly associated with schizophrenia across at least two independent samples." (PMID 36890161, 2023). "We concluded that we identified a significant, functional, and robust risk variant block covering entire KTN1 that might play a critical role in the risk and pathogenesis of schizophrenia." (PMID 36890161, 2023). "This hypothesis well interpreted how the associations between schizophrenia-risk KTN1 alleles and increased cortical volumes co-existed with the associations between schizophrenia and reduced cortical volumes in some brain areas." (PMID 36890161, 2023). "Finally, we found that the schizophrenia-risk alleles increased the SA of lingual gyrus and the TH of fusiform gyrus, but decreased the KTN1 mRNA expression in occipital cortex (in BRAINEAC), and the TH of pericalcarine cortex." (PMID 36890161, 2023). "We identified a significant, functional, and robust risk variant block at KTN1 for schizophrenia." (PMID 36890161, 2023). "In this study, the role of KTN1 variants in risk and pathogenesis of schizophrenia was explored." (PMID 36890161, 2023). "The patterns of allele-schizophrenia associations and regulatory effects were highly consistent, replicable and robust, supporting that the KTN1 variants may be biologically functional and play a critical role in the development of schizophrenia." (PMID 36890161, 2023). "We noticed that the potential regulatory effects of schizophrenia-risk alleles on KTN1 mRNA expression in putamen were opposite between BRAINEAC and GTEx, which may be attributed to cohort heterogeneity." (PMID 36890161, 2023).
schizophrenia (continued). "The schizophrenia-risk alleles suggestively or significantly increased the KTN1 mRNA expression in BG (putamen, caudate nucleus, nucleus accumbens, and/or substantia nigra) in GTEx, but decreased the expression in BG (putamen) suggestively in BRAINEAC, and all four BG GMVs significantly." (PMID 36890161, 2023). "One of these proteins is kinectin 1, as would be evidenced by our finding that the schizophrenia-risk alleles increased the KTN1 mRNA expression in most cortices examined, which may then increase the kinectin expression in neurons, expand the cell sizes, and increase the volumes of the cortices." (PMID 36890161, 2023). "A hypothesis of compensation may be able to interpret these contradictory findings: First, other schizophrenia-risk non-KTN1 genes might be dominant in these areas, significantly decreasing the volumes of cortices and thus the neurotransmission in the “cortico-BG-thalamo-cortical” loop." (PMID 36890161, 2023). "A dense set of SNPs (n = 849) covering entire KTN1 was analyzed in three independent European- or African-American samples (n = 6704) and one mixed European and Asian Psychiatric Genomics Consortium sample (n = 56,418 cases vs. 78,818 controls), to identify replicable SNP-schizophrenia associations." (PMID 36890161, 2023). "Interestingly, all of the effective alleles that increased KTN1 mRNA expression (t > 0) in GTEx were schizophrenia-risk alleles that increased risk for schizophrenia, and all effective alleles potentially increasing mRNA expression in BRAINEAC were schizophrenia-protective alleles." (PMID 36890161, 2023). "In summary, this is a study on the role of KTN1 in schizophrenia." (PMID 36890161, 2023). "Finally, this expression activation of volume-expanding KTN1 in cortices did not appear to restore the reduced volumes of cortices and neurotransmission of the loop resulting from other dominant schizophrenia-risk genes, suggesting that KTN1 played a “recessive” role in these areas." (PMID 36890161, 2023). "However, the role of KTN1 in schizophrenia has not been explored yet." (PMID 36890161, 2023).
bladder cancer (1 paper, 2021). "In bladder cancer, it was confirmed that lncRNA KTN1 AS1 overexpression promotes the recruitment of a histone acetyltransferase EP300." (PMID 34219129, 2021).
cognitive decline (1 paper, 2017). "The most significant association with cognitive decline was within the KTN1 gene containing the SNP rs12895072 and SNP rs12434554 (Padjusted = 4.2 × 10–9, Padjusted = 4.7 × 10–9) at 14q22." (PMID 28953682, 2017).
colorectal cancer (1 paper, 2016). A primary or metastatic malignant neoplasm that affects the colon or rectum. "Recently, FAT atypical cadherin 3 (FAT3), kinectin 1 (KTN1), discs large homolog 2 (DLG2) and deleted in colorectal cancer (DCC) have been reported to be associated with the function of the human mesolimbic reward system, which is the neurobiological basis of drug addiction." (PMID 27676367, 2016).
Parkinson disease (1 paper, 2020). A progressive degenerative disorder of the central nervous system characterized by loss of dopamine producing neurons in the substantia nigra and the presence of Lewy bodies in the substantia nigra and locus coeruleus. "Bioinformatics of KTN1 SNPs significantly associated with Parkinson’s disease in three independent European-American samples." (PMID 32655362, 2020). "The KTN1 mRNA expression in putamen or substantia nigra with/without Parkinson’s disease (PD) in five independent cohorts." (PMID 32655362, 2020).
squamous cell lung carcinoma (1 paper, 2014). A carcinoma arising from squamous bronchial epithelial cells. "In this case, a partial KTN1 pseudogene inserted into the last intron of PSD3 in a primary squamous cell lung cancer." (PMID 24714652, 2014).
viral infection (1 paper, 2024). "Interestingly, according to Gene Ontology, TMED10 and KTN1 are not directly related to immune responses, but their products interact with SARS-CoV-2 proteins, suggesting a role in the viral infection." (PMID 38637586, 2024).
cancer (13 papers, 2011 to 2025). A tumor composed of atypical neoplastic, often pleomorphic cells that invade other tissues. "Given the role of epithelial-mesenchymal transition (EMT) in cancer metastasis mechanisms, we further examined the levels of KTN1 expression and EMT biomarkers in these cells." (PMID 34219129, 2021). "A potential linkage has also been suggested between KTN1 and cancer, and KTN1has been proposed to participate in protein synthesis." (PMID 34689164, 2021). "KTN1 primarily participated in the cell cycle, DNA replication, and microRNAs in cancer pathways in HCC tissues." (PMID 34234850, 2021). "Studies have confirmed several roles of KTN1 in certain cancers." (PMID 34234850, 2021). "Further investigation into the function of KTN1 in ER is warranted and may demonstrate new promising regulatory networks for ER stress in tumorigenesis and cancer treatment." (PMID 34689164, 2021). "However, the molecular mechanism by which KTN1 promotes cancer cell growth remains largely unexplored." (PMID 34219129, 2021). "Moreover, in human HCC tissues, KTN1 may participate in the cell cycle, DNA replication, and microRNAs in cancer pathways." (PMID 34234850, 2021). "In functional studies, knockdown of KTN1 inhibited the proliferation and invasiveness of TNBC both in vitro and in vivo, while overexpression of KTN1 promoted cancer cell proliferation and invasiveness." (PMID 34219129, 2021). "KTN1 has been shown to directly bind kinesin, and a current research focus involves identifying inhibitors of kinesin spindle protein (KSP) as targets for multi-cancer therapy." (PMID 34689164, 2021).
tumor (10 papers, 2019 to 2025). "By examining the mutated genes, we found that tumor cells progressively acquired non-synonymous mutations in genes such as KTN1, ALB, APOB, CDK11A, and CDK11B." (PMID 41373592, 2025). "Furthermore, functional studies suggested that overexpression of KTN1 accelerated the proliferation, migration, and invasion of TNBC cells, and loss of KTN1 inhibited the growth of xenograft tumor in vivo." (PMID 34219129, 2021). "Furthermore, KTN1 was confirmed to be a pathogenic autoimmune antigen in several diseases 38, 39, suggesting its role KTN1in regulating immune systems and being involved in tumor immunity." (PMID 34234850, 2021). "Intriguingly, KTN1 expression in platelets was also dysregulated, suggesting a complex platelet-tumor interaction." (PMID 40948741, 2025). "We found an interesting point that the expression of KTN1 in TEPs is opposite to the expression in tumor cells and tissues." (PMID 40948741, 2025). "The results showed that the xenograft tumor growth was notably increased in KTN1-overexpressed groups, compared with the vector control groups (n = 6)." (PMID 34219129, 2021). "In this study, we found that KTN1 was significantly upregulated in both TNBC tumor specimens and cells, and this upregulation positively associated with poor prognosis of TNBC patients." (PMID 34219129, 2021). "Mechanistically, reduced platelet miR-199b-3p in LAC likely derepresses KTN1, mirroring its established tumor-promoting functions: CRISPR/Cas9 studies confirm KTN1 knockout suppresses proliferation, inhibits migration/invasion, and dysregulates innate immune responses in HCC/TNBC models." (PMID 40948741, 2025). "Our previous study suggested that KTN1 promoted epithelial‐to‐mesenchymal transition (EMT) progression in triple negative BCa, whereas inhibition of KTN1 expression could repress tumor EMT in vitro and in vivo." (PMID 35811688, 2022). "The treatment with CXCL8 siRNA oligos in KTN1-upregulated groups reduced the tumor growth." (PMID 34219129, 2021). "Moreover, KTN1 overexpression could promote cell proliferation and migration in cutaneous squamous cancer cells, indicating a functional role of KTN1 in invasive tumor growth." (PMID 35811688, 2022). "To explore whether KTN1 may specifically regulate EGFR protein levels in tumor cell lines, we transfected siKTN1 and siKTN1# into the human immortalized keratinocytes cell line HaCaT, in addition, KTN1mut was also transfected into the cell line to demonstrate the gene-specific of siKTN1." (PMID 34689164, 2021). "KTN1 binds PRMT1 and prevents its degradation, thereby potentiating β‐catenin signaling; suppressing the cGAS–STING pathway to sustain a “cold‐tumor” phenotype." (PMID 41256732, 2025). "In this study, we demonstrate that CCDC40 is upregulated by KTN1 depletion, which triggers the CCDC40-ADRM1-UCH37 regulatory axis as an anti-tumor pathway in cSCC." (PMID 34689164, 2021). "Collectively, these results reveal that knockdown of KTN1 reduces EGFR protein expression post-transcriptionally and serves as a tumor suppressor strategy by increasing apoptosis and repressing the survival fraction in cSCC cells." (PMID 34689164, 2021). "KTN1 knockdown increases the expression of CCDC40, PSMA1, and ADRM1 to mediate tumor suppressor functions in vivo and in vitro." (PMID 34689164, 2021). "In this study, we demonstrate that KTN1 knockdown induces EGFR degradation in cSCC cells by promoting the ubiquitin-proteasome system, and that this effect is tumor cell-specific." (PMID 34689164, 2021). "Finally, the peptide list suggested the presence of increased Kinectin 1, Coronin 1, and ALPK3 expression in both tumor types (HCC and iCCA)." (PMID 37046807, 2023). "However, our findings suggested that increased YY1 expression expedited tumor cell EMT and aggressive growth in high‐grade BCa by transactivating the KTN1 gene." (PMID 35811688, 2022). "Second, the biological effect and pro-tumor role of KTN1 in HCC was not verified on the in vivo level." (PMID 34234850, 2021).
tumor (continued). "However, the tumor growth was significantly reduced in mice bearing tumors expressing CXCL8 siRNA oligos groups, compared with the KTN1 overexpression groups (n = 6)." (PMID 34219129, 2021). "Knockdown of KTN1 reduced the primary tumor growth as compared with the negative control groups (NC) after injection of tumor cells at 63 days." (PMID 34219129, 2021).
neurodegenerative disease (2 papers, 2020 to 2022). A disorder of the central nervous system characterized by gradual and progressive loss of neural tissue and neurologic function. "KTN1 variants have also been associated with several other neuropsychiatric or neurodegenerative diseases/phenotypes before, including attention-deficit/hyperactivity disorder (ADHD), substance use disorder (SUD), and cognitive dysfunction in the elderly." (PMID 32655362, 2020).
brain disorder (1 paper, 2020). A disease affecting the brain or part of the brain. "Neurons with more kinectin 1 have larger cell bodies, and thus may increase the putamen and SNc GMVs in subjects without brain disorders." (PMID 32655362, 2020).
connective tissue disorder (1 paper, 2014). A disease involving the connective tissue. "KTN1 is involved in molecular transport, RNA trafficking, connective tissue disorders pathway of depressed women, but also in infectious disease, cellular assembly and organization, cellular function and maintenance pathway of antidepressant-treated women." (PMID 25628539, 2014).
KTN1 also shares sentences with these, for which no sentence is quoted: cervical cancer (2 papers); melanoma (2); glioblastoma (1); glioma (1); hearing loss (1); heroin addiction (1); infectious disease (1); Obesity (1); ovarian carcinoma (1); triple-negative breast carcinoma (1); type 2 diabetes (1).